MGMT (O-6-methylguanine-DNA methyltransferase)
Diseases named in the same sentence as MGMT in open-access papers (continued):
Sharing a sentence is not in itself a finding about the gene and the disease.
tumor (continued). "The median age at baseline was 59 years, 293 (59.8%) were male and 197 (40.2%) female, 51 (11% of 482 patients with available data) had IDH1 or IDH2 mutations detected in their tumours, and 234 (51% of 456) of patients had methylation of the MGMT promotor." (PMID 35804940, 2022). "Tumours which are MGMT deficient develop acquired mismatch repair deficiency as a resistance mechanism to TMZ treatment." (PMID 36050653, 2022). "On the other hand, the reduced cancer risk due to MGMT overexpression also reveals its tumor suppress activity." (PMID 34544433, 2021). "The relationships between IDH1 mutation and MGMT promoter methylation with the type of chemotherapies were also assessed independently with tumor recurrence interval." (PMID 34257620, 2021). "The impact of the isocitrate dehydrogenase 1 (IDH1) mutation together with the methylation status of O6-methylguanine-DNA methyltransferase (MGMT) on RT-induced anti-tumor immunity against GBM is unclear." (PMID 34094969, 2021). "MGMT inhibition promotes cell proliferation via p21, P27, and Cyclin E. Low-expression MGMT in tumor tissues is associated with worse clinicopathological features and outcomes." (PMID 34868996, 2021). "Where possible, we also analyzed tumor molecular subgroups classified according to either IDH mutation or MGMT methylation status, the minimal size of a subgroup was ten samples." (PMID 34439271, 2021). "We found that allelic loss in both D10S173 (ADD3/MXI1 locus) and D10S1137 (MGMT locus) were positively associated with tumor grading and proliferative index (MIB-1)." (PMID 34970477, 2021). "Clinical factors associated with the ME distance included tumor grade, MGMT methylation status, IDH mutation, and 1p/19q co-deletion (all P < 0.05)." (PMID 34784919, 2021). "Our results showed that the number of lobes involving the tumor, MGMT methylation, IDH mutation, and adjuvant TMZ chemotherapy cycles (HR:0.454; P:0.01) are factors related to tumor progression." (PMID 34724914, 2021). "Different studies have evaluated possible associations between MGMT methylation and tumor vascularity." (PMID 33001310, 2021). "As the pivotal repair gene for DNA alkylation damage, MGMT inactivation has been reported to be a common event in several kinds of cancer and associated with increased frequency of tumor-associated genes mutations." (PMID 34544433, 2021). "MGMT promoter methylation can cause MGMT expression deficiency, thereby promoting tumor cell sensitivity to alkylating drugs, such as TMZ." (PMID 34970146, 2021). "Recursive partitioning analysis stratified the patients in the WVRT (–) group at higher intraventricular failure risk (2-year survival, 14.2%) due to tumor ventricular involvement, MGMT unmethylation, and ventricle opening." (PMID 34621677, 2021). "O-6-methylguanine-DNA methyltransferase (MGMT) encodes a DNA damage repair protein that protects tumor cells against DNA double-strand breaks caused by alkylating agents, such as TMZ." (PMID 34123852, 2021). "For example, thus far only three tumor subtypes, four cancer stem cell transcriptional states and a few biomarker-based predictors of therapy response (MGMT methylation and IDH1 mutation) have been described." (PMID 33919246, 2021). "The main clinical data collected included tumor characteristics, status of MGMT promoter, and IDH mutation, number of relapse, response, survival, adverse reactions, and salvage therapies." (PMID 33634023, 2020). "A high immunoreactivity of ALDH1A3 in tumor infiltrative area was associated with shorter OS, especially in patients with MGMT promoter methylation." (PMID 32680476, 2020). "In circulating tumor cells, MGMT promoter hypermethylation was associated with a better response to nCRT." (PMID 33105711, 2020).
tumor (continued). "Molecular groups of IDH1, TERT, and 1p/19q and IDH1 and MGMT were independently associated with tumor growth." (PMID 32388499, 2020). "MGMT protein is a kind of DNA repair enzyme, which can protect normal tissues from alkylating agent damage, reduce cancer, and also cause tumor tissue resistance to alkylating agent chemotherapy." (PMID 32086739, 2020). "In univariable analysis, TERT promoter mutation C250T was significantly associated with increased tumor growth (+ 52.4 mm/year), while MGMT promoter methylation was significantly associated with decreased tumor growth (-37.4 mm/year)." (PMID 32388499, 2020). "Although several DNA repair mechanisms are involved in the repair of TMZ-induced lesions, TMZ resistance in the clinic has so far been associated mainly with the activity of MGMT and the selection of resistant clones that account for tumor recurrence." (PMID 32927769, 2020). "After adjustment for WHO grade, ATRX, Ki67 and TERT, the molecular groups of IDH1 and MGMT were independently associated with tumor growth." (PMID 32388499, 2020). "Next, the same Cox regression analysis was repeated including clinical variables, like tumor malignancy, MGMT promoter methylation status, IDH1 mutation status, and patient gender and age (<50 or ≥50 years)." (PMID 33227903, 2020). "No statistical association between the methylation status of the MGMT promoter (clinical information) and observed tumour take in mice was found." (PMID 32260145, 2020). "MGMTp methylation silences the MGMT gene and reduces the ability of tumor cells to repair damage caused by temozolomide and other alkylating agents." (PMID 33066633, 2020). "According to the standard, 36 high-risk patients with unmethylated MGMT were enrolled in the cohort, all of whom were upgraded to sGBM upon tumor recurrence." (PMID 33392065, 2020). "The IDH1, TERT, and 1p/19q; and IDH1 and MGMT molecular groups were independently associated with tumor growth." (PMID 32388499, 2020). "Molecular tumor related factors include methylation status of the O6-methylguanine-DNA methyltransferase (MGMT) promoter and mutation status of isocitrate dehydrogenase 1 and 2 (IDH 1/2) which are highly specific for secondary GBM." (PMID 31831026, 2019). "For instance, demethylation of MGMT promoter in tumor tissue seemed to be associated with higher risk of recurrence in general, and specifically in patients who received adjuvant chemotherapy." (PMID 31390840, 2019). "Previous studies have verified that certain radiological characteristics on MR images such as tumour necrosis, enhancement patterns and tumour location are associated with MGMT promoter methylation." (PMID 30039219, 2019). "Since O6MeG induced by TMZ (and other methylating anticancer drugs) is a toxic DNA damage, it is understandable that MGMT deficiency (determined, e.g., by promoter methylation) leads to responsiveness of the tumor." (PMID 30925722, 2019). "Temporal tumor location and MGMT promoter methylation were significantly associated with survival among PGS patients, supporting the relevance of future studies of RT/TMZ therapy treatment in GS patients to include evaluation of these characteristics." (PMID 31921679, 2019). "The subgroup of patients with methylated MGMT promoter in the primary tumor displayed a significant loss of methylation if treated with concurrent RT/TMZ (7 of 8) compared to patients treated with RT followed by sequential TMZ (1 of 5, p = 0.03)." (PMID 31766430, 2019). "Factors significantly associated with OS included temporal tumor location (temporal vs. other, HR: 0.41, p = 0.036) and MGMT promoter methylation (methylated vs. unmethylated, HR: 0.17, p = 0.022)." (PMID 31921679, 2019). "Temporal tumor location and MGMT status were found associated with PGS survival (p = 0.036 and p = 0.022, respectively)." (PMID 31921679, 2019).
tumor (continued). "Epigenetic silencing of the MGMT gene by promoter methylation reduces DNA-repair activity and enhances the susceptibility of cells to mutagenic events, resulting in inactivation of tumor suppressor genes, genomic instability and tumor formation." (PMID 31362435, 2019). "Undetectable MGMT activity was found in as few as 10% cases, and the frequency of MGMT-deficiency was 7-fold lower in tumours recurring after alkylating agent chemotherapy." (PMID 35582280, 2019). "Agarwal noted that after TMZ therapeutic failure there was generally an upregulation of MGMT or there was a downregulation of canonical MMR (or mutations in MutSa/MutLa) in second resection tumor samples." (PMID 29844863, 2018). "On the other hand the therapeutic response to alkylating agents is improved in tumor cells with hypermethylation in MGMT causing its silence resulting either in low levels or complete loss of MGMT expression." (PMID 29712977, 2018). "In the present study, we revealed that the methylation status of the MGMT promoter in IDH-wild-type GBM was associated with conventional structural image features (tumor location and necrosis)." (PMID 29467012, 2018). "High MGMT expression in glioma cells is the predominant mechanism underlying tumor resistance to alkylating agents." (PMID 29619003, 2018). "Altogether, these results present loss of MSH6 expression as a protective backup mechanism of tumor cells under conditions of inactivated MGMT." (PMID 30274152, 2018). "Another striking result of our study is that poor survival associated with an unmethylated MGMT promoter is detected only in aged patients who have undergone chemoradiotherapy after maximal safe resection of the tumor." (PMID 29984907, 2018). "Age and MGMT promoter methylation were identified as independent prognostic biomarkers, and the TERT promoter mutation status and MGMT promoter methylation status, when combined with other tumor‐related factors, generated several different survival subgroups." (PMID 29984907, 2018). "The methylation status of the MGMT promoter in IDH-wild-type GBM was associated with conventional structural image features (tumor location and necrosis)." (PMID 29467012, 2018). "Increased MGMT expression is a hallmark of the tumor phenotype and directly correlates to the degree of local and distant tumor invasiveness." (PMID 30038716, 2018). "In our in vivo study, miRNA-370-3p plays a tumor-suppressive role, and this role is associated with the MGMT and FOXM1 downexpressions, while the expressions of TGFβ-RII and FOXO1 remain unchanged." (PMID 30497054, 2018). "The O6-methylguanine-DNA methyltransferase (MGMT) methylation tumor's status has been associated with pseudoprogression occurrence and 2/3 of MGMT methylated tumors exhibit pseudoprogression, 11% early progression, and 25% stable disease." (PMID 30627060, 2018). "Low basal expressions of the tumor MGMT protein and the MGMT promoter hyper-methylation are each associated with prolonged survival for GBM patients treated with TMZ." (PMID 29301329, 2018). "Whereas the mechanism of temozolomide involves damage to tumor DNA leading to apoptosis, tumor resistance is associated with DNA damage repair through the O6-methylguanine-DNA-methyltransferase (MGMT) enzyme." (PMID 30583528, 2018). "A significant but only weak association between the MGMT score and tumor sample purity was detected for EORTC 22033 (p value = 0.0013, Wald test based on robust estimation)." (PMID 29368212, 2018). "Similar to the original hypermethylated GBM12 tumor, the placebo-treated 5199 line had low MGMT protein expression and was highly susceptible to TMZ." (PMID 30054476, 2018). "The first step (i.e. DIX phase) includes temozolomide treatment in two types of patients, i.e. those bearing MGMT-deficient neoplasia, or those affected by MGMT-proficient malignancy." (PMID 28404974, 2017).
tumor (continued). "MGMT is a key gene that encodes a protein that repairs DNA, while methylation suppresses the DNA repair activity, including DNA in the tumor that is actively dividing." (PMID 29255149, 2017). "Prognosis in GBM patients has been associated with various factors including age, tumor size, extent of tumor resection of >98%, tumor location and O6-methylguanine methyltransferase (MGMT) promoter methylation." (PMID 28423669, 2017). "Methylation of individual CpG sites in these islands of the MGMT promoter was shown to correlate with loss of MGMT protein expression in the tumor tissue." (PMID 27158275, 2016). "Patient characteristics and genetic markers (IDH-1 mutation, MGMT promoter methylation and the subtype genetic signature of the respective tumor samples) were assessed." (PMID 26978262, 2016). "Tumour hypoxia is also associated with increased expression of O6-methylguanine-DNA-methyltransferase (MGMT), a DNA repair protein involved in resistance to temozolomide." (PMID 26966676, 2016). "It has been reported that while MGMT is expressed in all normal human cell types and tissues, 20%–30% of human tumor or more than 50% of virally transformed cell lines are completely deficient in MGMT expression." (PMID 29061931, 2015). "The DNA repair enzyme O6 methylguanine DNA methyltransferase (MGMT) causes resistance of tumor cells to bifunctional nitrosourea, like lomustine." (PMID 29061931, 2015). "Our in vitro results reveal a significant association between MGMT expression in tumor cells and TMZ resistance." (PMID 26447477, 2015). "In our study, the methylation status of MGMT in tumor-distant tissues was associated with tumor grading." (PMID 26370119, 2015). "Numerous carcinogens target O6-guanine, thus, the loss of MGMT gene expression results in the accumulation of unrepaired DNA damage and subsequent tumor development." (PMID 25452816, 2015). "The methylation status of MGMT in tumor-distant tissues was associated with tumor grading (p = 0.019)." (PMID 26370119, 2015). "MGMT promoter methylation, well known as one of the proposed mechanisms underlying suppression of MGMT expression, is associated with the reduced MGMT protein level commonly seen in primary human neoplasms." (PMID 26400193, 2015). "The methylation status of the promoter region of MGMT is one of the most promising prognostic biomarkers of GBM: a methylated MGMT promoter is associated with a more effective tumor response to temozolomide and increased survival of GBM patients." (PMID 25762636, 2015). "We found that PTEN mutation and MGMT promoter methylation are significantly increased with increasing tumor grade from 3.5% and 30.4% in AII to 17.6% and 62.5% in AIII." (PMID 25333259, 2014). "O6-methylguanine-DNA methyltransferase (MGMT) promoter methylation silences the MGMT gene, decreasing DNA repair activity and increases the susceptibility of tumor cells to chemotherapeutic agents." (PMID 25228849, 2014). "Various human tumor cell lines and xenografts have been used to demonstrate the association between the activity of MGMT and the ability to withstand methylating agents and alkylating nitrosoureas." (PMID 24932232, 2014). "MGMT methylation had an increased risk in tumor tissue (OR = 4.43; 95% CI: 2.85, 6.89) in comparison with non-cancerous samples including plasma, tissue, and bronchoalveolar lavage fluid." (PMID 24086261, 2013). "Methylation of MGMT gene promoter has been associated with loss or decrease of MGMT expression in tumor tissues of various cancers, including lung tumors." (PMID 24086261, 2013). "PIK3CA-mutated tumors were associated with loss of MGMT expression (35% vs. 20%; P = 0.001) and the presence of tumor mucinous differentiation (54% vs. 32%; P<0.001)." (PMID 23785428, 2013).
tumor (continued). "CcO status appears to be a robust prognostic factor when compared with the most reliable predictor of tumor susceptibility, MGMT promoter methylation." (PMID 23593382, 2013). "MGMT promoter methylation was present in 27% of tumor samples and was associated to a higher overall survival (66 weeks vs 30 weeks, p<0.004)." (PMID 23922679, 2013). "For instance, DNA hypermethylation of MGMT promoter in 40% of glioma patients is directly associated with the tumor resistance to conventional chemotherapy based on alkylating agents." (PMID 23873296, 2013). "Evidence supporting this role of MGMT comes from clinical studies indicating that hypermethylation of the promoter of MGMT is associated with improved tumor response and survival in patients with GBM." (PMID 22396071, 2012). "Methylation of the MGMT promoter in GBM patients correlates with increased susceptibility of the tumor to the alkylating agent therapy." (PMID 22912934, 2012). "High rate of MGMT protein positivity (> 20% positive neoplastic nuclei) was inversely associated with pre-operative tumor necrosis (p = 0.021)." (PMID 22214427, 2012). "Formaldehyde-responsive miRNAs predicted to modulate MAM-associated genes in the brains of MGMT-deficient mice include miR-17-5p and miR-18d, which regulate genes involved in tumor suppression, DNA repair, amyloid deposition, and neurotransmission." (PMID 23060898, 2012). "This study further showed that patients whose tumor had a methylated promoter for the gene encoding O6-methylguanine-DNA methyltransferase (MGMT) were more likely to benefit from the addition of TMZ." (PMID 24212792, 2011). "This condition is thus similar to a tumor population of cells in which the MGMT is methylated at one of the two alleles." (PMID 20167086, 2010). "Seventeen cases (17/149, 11.4%) of tumours showed complete loss of MGMT expression and 13 cases of these (76.5%) were methylated in promoter region." (PMID 12085181, 2002). "Loss of MGMT expression was found in 13.3% of tumours and was significantly associated with pTNM stage (P=0.037), and tumour invasion (P=0.02)." (PMID 12085181, 2002). "Out of the 132 tumours with MGMT expression, eight tumours (6.1%) showed methylation, and among these eight cases, three showed loss of MGMT expression in the focal area of the tumour." (PMID 12085181, 2002). "Resistance of tumour cells to methylating and monochloroethylating agents in vitro and in vivo has been linked to levels of the DNA repair protein O6-methylguanine-DNA methyltransferase (MGMT)." (PMID 9820180, 1998). "However, younger age, MGMT methylation, smaller residual tumor volume, and later recurrence were linked to better survival outcomes, underscoring their prognostic importance." (PMID 42187555, 2026). "In addition, tumor resistance to dacarbazine is frequently associated with the upregulation of the DNA repair enzyme O6-methylguanine-DNA methyltransferase (MGMT), which counteracts DNA alkylation and reduces treatment efficacy." (PMID 41471839, 2025). "Thus, future studies should take multiple factors into consideration, looking for a linked correlation between the overall tumor image and MGMT status, instead of focusing on a singular ROI." (PMID 41476598, 2025). "Our study sought to demonstrate whether loss of MGMT protein expression is associated with improved overall survival (OS) in patients receiving CAPTEM for NENs from various tumor sites." (PMID 39825572, 2025). "A major finding of this study is the demonstration that MGMT inhibition through these redox-sensitive protein modifications occurs fairly rapidly to create an MGMT-deficient state, just similar to that engineered by O6-benzylguanine in tumor cells." (PMID 39997039, 2025). "Traditionally, TMZ-resistance was primarily linked to the MGMT status of the tumor cells." (PMID 39989968, 2025).